C3orf36 (chromosome 3 putative open reading frame 36)
Synonyms: FLJ22173
Gene: Long non-coding RNA gene on chromosome 3 (133,928,145 to 133,929,812, reverse strand). Ensembl gene ENSG00000288547.
Diseases named in the same sentence as C3orf36 in open-access papers:
C3orf36 is named in the same sentence as 4 diseases in open-access papers, as found by Europe PMC text mining. Sharing a sentence is not in itself a finding about the gene and the disease. The quoted sentences say what the papers report.
cancer (1 paper, 2026). A tumor composed of atypical neoplastic, often pleomorphic cells that invade other tissues. "The model identified key genes such as C3orf36, JHY, and TASP1, showing significant differences in mutation counts across cancers." (PMID 41870130, 2026).
neurological disorders (1 paper, 2017). "Three genes are involved in developmental and neurological disorders: C3orf36, CDK5RAP2, CRY2." (PMID 29259192, 2017).
C3orf36 also shares sentences with these, for which no sentence is quoted: osteosarcoma (1 paper); Sepsis (1).